TEK (TEK receptor tyrosine kinase)
Diseases named in the same sentence as TEK in open-access papers (continued):
Sharing a sentence is not in itself a finding about the gene and the disease.
tumor (continued). "Angiopoietin-1/TEK signaling is important for vascular integrity, TEK knockout results in a significant increase in metastatic tumor cells in the lung." (PMID 33602230, 2021). "Tyrosine kinase endothelial (TEK), also called TIE2, is an effective target for malignancy treatment by inhibition of tumor angiogenesis through ANG2/TIE2 axis." (PMID 33681207, 2021). "ANGPT1 encodes a secreted glycoprotein that belongs to the angiopoietin family and plays an important role in tumor vascularization as an agonist of angiogenic receptor TEK." (PMID 29113349, 2017). "Using transgenic animals in which GFP was under control of the Tie2 (TEK) promoter, we were able to visualize BM-EPC association with tumor blood vessels." (PMID 21609465, 2011). "Additionally, TEK mediates interactions between endothelial and tumor cells, contributing to extracellular matrix remodeling and enhancing tumor cell migration." (PMID 40665092, 2025). "Finally, we investigated the therapeutic potential of shikonin, demonstrating its anti-tumor effects via modulation of the TEK-AKT/mTOR signaling pathways." (PMID 40808675, 2025). "TEK was originally thought to be a specific receptor for endothelial cells, which plays an important role in the regulation of angiogenesis and remodeling and influences the formation of the tumor microenvironment." (PMID 35222525, 2022). "TEK expression was significantly correlated with tumor purity (p = 4.29e-16)." (PMID 36686655, 2022). "We next quested whether the loss of Mettl3 was able to inhibit the expression of specific targets involved in tumor angiogenesis such as TEK and VEGF-A." (PMID 33681207, 2021). "Finally, we confirmed the high expression of TEK in ccRCC and its tumor-promoting mechanism through cellular functional experiments." (PMID 33602230, 2021). "Furthermore, TEK activation normalizes the structure and function of tumor vessels, thereby delaying tumor growth, slowing the metastatic process and enhancing the response to concomitant cytotoxic treatments." (PMID 33602230, 2021). "We selected these genes because all six were present in the angiogenesis signature unique to PDAC, because CYP1B1 was the most significantly and highly up-regulated, and because ANGPT1, its receptors TIE1 and TEK, and HIF1A are commonly associated with pathways that enhance tumor angiogenesis." (PMID 26586478, 2016). "Third, while our findings suggest that TEK mediates the anti-tumor effects of shikonin, the exact molecular mechanism, such as how shikonin upregulates TEK or enhances its interaction with downstream effectors, remains unclear and requires further investigation." (PMID 40808675, 2025). "Specifically, MYOC, TBK1, COL1A1, and COL1A2 were upregulated in tumor tissues, while FOXC1, LRP2, and TEK was downregulated (all p < 0.05)." (PMID 40808675, 2025). "Our results uncovered the predominant expression of ANGPT2 and TEK in HUVECs and HPMECs, whereas VEGF-A was expressed primarily in tumor cells." (PMID 40370455, 2025). "Regorafenib is an oral multi-targeted TKI, whose targets are involved in the regulation of tumor angiogenesis (VEGFR1–3 and TEK), oncogenesis (KIT, RET, RAF1, BRAF, and and BRAFV600E), and maintenance of the tumor microenvironment (PDGFRA, PDGFRB and FGFR)." (PMID 39165680, 2024). "The most important markers of TAMs have been identified by studying tumours at different sites: CD163, CD204 (MSR1), CD206 (MRC1), MARCO, SIGLEC1 (CD169), stabilising protein-1 (Stab1) and Tie2 (TEK)." (PMID 39060648, 2024). "These included well-known receptor tyrosine kinase genes (EGFR, TEK and OSMR) that activate MAPK and PI3K signaling pathways, and other tumor-promoter genes (ATP8B2, DAAM1, SLAMF8 and SRGN) as well as tumor-suppressor genes (A2M, DAPK1, RASSF8 and SOCS3)." (PMID 37190308, 2023). "Our results have revealed a novel mechanism of Mettl3 by which it mediates m6A modulation of TEK and VEGF-A to promote tumor angiogenesis." (PMID 33681207, 2021).
tumor (continued). "The mRNA levels of TEK, BMP1, AR, SLC11A1, SLC40A1, and F2RL1 were significantly downregulated in tumor cells compared with normal cells, and CX3CL1 and RNASE2 were upregulated in tumor cells." (PMID 35004689, 2021). "We then applied Integrative Genomics View (IGV) software to search for the possible targets based on our meRIP-seq datasets and found that m6A peaks were abundant upon TEK and VEGF-A genes that were responsible for tumor angiogenesis." (PMID 33681207, 2021). "Notably, IFN-γ was shown to suppress the mRNA expression of ANGPT2 and TEK in HUVECs and HPMECs and to inhibit the mRNA expression of VEGF-A in tumor cells." (PMID 40370455, 2025). "Furthermore, data generated from m6A-squencing portray a regulatory network of Mettl3-modulated TEK/PI3K/VEGF axis, which propels the angiogenesis surrounding tumor cells." (PMID 33681207, 2021). "Whether this finding could be due to a race-related difference in the tumor’s responsiveness to bevacizumab is deserving of further study to fully evaluate if ANGPT1, ANGPT2, TEK, FGF2, MMP9 and VEGFA are promising targets for future research." (PMID 28045923, 2017). "In addition to blocking VEGFR2, YLL545 altered the expression of other molecules involved in tumor angiogenesis, including ITGAV, ENG, THBS1, FN1, and TEK." (PMID 27203384, 2016). "In addition an inhibition of mast/stem cell growth factor (KIT), FMS-like tyrosine kinase 3 (FLT-3), TIE-2 (TEK tyrosine kinase, endothelial), tropomyosin-related kinase B (TRKB), and AXL lead to tumor regression." (PMID 27881963, 2016). "However, extensive mutational analysis of tumor genes could not identify predictive markers of regorafenib efficacy, including among genes involving in angiogenesis (FLT1, FLT2, FLT3, FLT4, KDR, TEK (TIE2), and VHL)." (PMID 33322802, 2020). "However, the effect on OS observed especially in the subgroup receiving cisplatin-based CHT may be of particular importance, considering that ANGPT/TEK, together with VEGF/VEGFR, regulate vascular stability and permeability, which are crucial for drug delivery to the tumor." (PMID 32526933, 2020). "The negative prognostic value of plasma TIE2/TEK in GBC mandates further investigation of proangiogenic and inflammatory activity in GBC tumor tissue." (PMID 37404757, 2023).
cancer (135 papers, 2007 to 2026). A tumor composed of atypical neoplastic, often pleomorphic cells that invade other tissues. "TEK (Tie2) is one of the RTKs that belongs to the TIE family and, along with VEGFR, encodes angiogenesis in cancer patients." (PMID 39330508, 2024). "The abundance of genes related to vascular stability (CDH5, CLDN5, TIE1, JAM2, TEK) indicated that the group with a lower cholesterol score had higher vascular stability, while low vascular stability often promotes cancer growth." (PMID 38023262, 2023). "SLC14A1 and TEK, underexpressed in the stage IV cancer (log2(FC) = -1.06, FDR = 0.0007; log2(FC) = -1.09, FDR = 9.26e-06), were two genes only regulated by GATA1." (PMID 25648588, 2014). "However, others such as PDGFR, VEGFR2, GR, and TEK are in vitro-confirmed and are highly validated oncology and immunology targets, offering a reason to use prednisone to treat cancer and immune-related indications in dog." (PMID 37888725, 2023). "The identified TEK p.R842H (c.2525G>A) mutation in current study is reported in the COSMIC (Catalogue of Somatic Mutations in Cancer) database, however the function of this mutation is not investigated." (PMID 35094709, 2022). "Dysregulated TEK expression has also been observed in several cancer, indicating that TEK expression may have prognostic value in these cancers." (PMID 33461176, 2021). "Given complex and still underexplored functions of the ANGPT/TEK system, the lack of functional research on these specific variants and the lack of data on their role in cancer, interpretation of our findings is difficult at this stage." (PMID 32526933, 2020). "This is also the first report concerning TEK rs639225 in relation to cancer disease." (PMID 32526933, 2020). "The results showed that TPX2 and BIRC5 were upregulated, while AGER, TEK, CLIC5, MAMDC2, EMCN, and SEMA3G were mostly downregulated in multiple cancer types." (PMID 40535574, 2025). "Merck’s angiogenic signature was selected as genes co-expressed with known angiogenic genes, KDR, TIE1, TEK, and CD34, in public pan-cancer genomic datasets." (PMID 39835481, 2025). "Although the only inhibitor in clinical trials, CFI-400945 exhibits considerable antiproliferative actions in cancer, it also has activity against AURKB, TRKA, TRKB, and Tie2/TEK." (PMID 33777739, 2021). "In our results, TMPO-AS1/miR-126-5p/SPP1 and CARD8-AS1/miR-21-5p/TEK are not only related to LUAD progression, but also function as immunotherapeutic targets for LUAD, clarifying a novel mechanism in cancer therapy." (PMID 34149807, 2021).
infection (27 papers, 2013 to 2025). The state of being infected such as from the introduction of a foreign agent such as serum, vaccine, antigenic substance or organism. "In Ebola infections in CC mice, a diverse phenotypic variation ranging from high resistance to complete lethality was observed across CC strains, and a central transcriptional regulatory gene called Tek (TEK receptor tyrosine kinase) correlated with weight loss and mortality after infection." (PMID 37420306, 2023).
adenocarcinoma (1 paper, 2021). A common cancer characterized by the presence of malignant glandular cells.
genetic disorder (1 paper, 2020). "Blue rubber bleb naevus syndrome (BRBNS) is a genetic disorder linked to TEK or TIE2 mutations." (PMID 32886264, 2020).
TEK also shares sentences with these, for which no sentence is quoted: Sepsis (75 papers); melanoma (26); endothelial dysfunction (25); atherosclerosis (18); psoriasis (12); endotoxemia (11); hepatocellular carcinoma (11); Hyperglycemia (11); malaria (11); breast tumor (10); pulmonary fibrosis (9); prostate carcinoma (8); Hypertension (7); primary open angle glaucoma (7); anemia (6); Arthritis (6); Cerebral ischemia (6); gastric cancer (6); pneumonia (6); type 2 diabetes mellitus (6); acute respiratory distress syndrome (5); cardiovascular diseases (5); cerebral malaria (5); cervical cancer (5); influenza (5); liver fibrosis (5); metastatic disease (5); Nephropathy (5); pancreatic neuroendocrine tumor (5); retinopathy (5).
A further 263 diseases each share a sentence with TEK in 5 papers or fewer.